SETD5 (SET domain containing 5)
Description:
Chromatin regulator required for brain development: acts as a regulator of RNA elongation rate, thereby regulating neural stem cell (NSC) proliferation and synaptic transmission. May act by mediating trimethylation of 'Lys-36' of histone H3 (H3K36me3), which is essential to allow on-time RNA elongation dynamics. Also monomethylates 'Lys-9' of histone H3 (H3K9me1) in vitro. The relevance of histone methyltransferase activity is however subject to discussion.
Synonyms: FLJ10707; SETD5A; MRD23
Tractability: PROTAC: ubiquitination databases record sites on it.
Gene: Protein-coding gene on chromosome 3 (9,397,609 to 9,479,240, forward strand). Ensembl gene ENSG00000168137.
Subcellular location: Nucleus; Chromosome
Subcellular location (Human Protein Atlas): Nucleoplasm; Cytosol
Gene Ontology:
Molecular function: histone H3K36 methyltransferase activity; histone H3K36 trimethyltransferase activity; histone H3K9 methyltransferase activity; histone H3K9 monomethyltransferase activity; transcription corepressor activity
Biological process: cognition; regulation of chromatin organization; regulation of DNA-templated transcription; regulation of DNA-templated transcription elongation; regulation of synapse assembly; chromatin remodeling; negative regulation of transcription by RNA polymerase III
Cellular component: nucleoplasm; chromatin; chromosome; euchromatin; nucleus; Rpd3L-Expanded complex; Set3 complex
Genetic constraint (gnomAD): Loss-of-function variants: 41 observed, 141.34 expected, observed/expected ratio (o/e) 0.29, 90% interval 0.22 to 0.38. The upper end of that interval is the gene's LOEUF score, 0.38, which puts it in group 1 of 6, group 1 being the genes least tolerant of losing a copy. Missense variants: 1,481 observed, 1,712.1 expected, observed/expected ratio (o/e) 0.87, 90% interval 0.83 to 0.9. Synonymous variants: 675 observed, 636.5 expected, observed/expected ratio (o/e) 1.06, 90% interval 1 to 1.13.
Gene-disease validity (ClinGen):
ClinGen rates the evidence that SETD5 causes each of these diseases.
syndromic complex neurodevelopmental disorder (autosomal dominant): Definitive. A disorder that involves more than one phenotype associated with the central nervous system, including but not limited to intellectual disability, autism, and seizures (epilepsy), and also a distinctive pattern of other features including dysmorphisms and/or congenital malformations.
Homologues: Orthologues: chimpanzee SETD5 (99% identical), macaque SETD5 (98% identical), pig SETD5 (96% identical), dog SETD5 (95% identical), mouse Setd5 (94% identical), rat Setd5 (93% identical), guinea pig SETD5 (90% identical), rabbit SETD5 (89% identical), tropical clawed frog setd5 (60% identical), zebrafish setd5 (36% identical), Drosophila melanogaster upSET (21% identical), Caenorhabditis elegans set-26 (15% identical), and 2 more. Paralogues in human: KMT2E (33% identical).
Diseases named in the same sentence as SETD5 in open-access papers:
SETD5 is named in the same sentence as 62 diseases in open-access papers, as found by Europe PMC text mining. Sharing a sentence is not in itself a finding about the gene and the disease. The quoted sentences say what the papers report.
Intellectual disability (15 papers, 2016 to 2025). "Recent studies suggest a possible association between variants in SETD5 and epilepsy, particularly in individuals with intellectual disability and developmental delay." (PMID 40462669, 2025). "For this purpose, we tested a genetic haploinsufficiency ASD mouse model affecting the SET-domain containing 5 (Setd5), a histone-associated protein found in approximately 1% of patients with intellectual disability and ASD." (PMID 38857283, 2024). "Monoallelic alterations of the SETD5 gene are implicated in intellectual disability, combining delayed psychomotor development and poor language development (OMIM #615761)." (PMID 36765386, 2023). "DD was caused by SETD5 mutation inherited from his mother with intellectual disability and growth delay was caused by ACAN mutation inherited from his father with short stature." (PMID 32595695, 2020). "SETD5, a gene linked to intellectual disability (ID) and autism spectrum disorder (ASD), is a member of the SET-domain family and encodes a putative histone methyltransferase (HMT)." (PMID 30655503, 2019). "Loss of function mutation in SETD5 was associated with mental retardation, intellectual disability, delayed speech and so forth." (PMID 27099631, 2016). "Haploinsufficiency of the SETD5 gene, encoding a SET domain-containing histone methyltransferase, has been identified as a cause of intellectual disability and Autism Spectrum Disorder (ASD)." (PMID 36613611, 2022). "Although recent studies have suggested that SETD5 and SRGPA3 are the key genes involved in intellectual disability in 3p deletion syndrome, the genetic test results in the present case showed that BRPF1 deletion may also cause intellectual disability." (PMID 33643973, 2021). "The duplication of a natural splice site in SETD5 identified in patient 5 in the heterozygous state, absent from the gnomAD database, and annotated as frameshift would have been consistent with the previous descriptions, where the intellectual disability is often mild." (PMID 36765386, 2023).
breast carcinoma (8 papers, 2015 to 2023). "In most cases, the upregulation of SETD5 is detected in pancreatic cancer, breast cancer, esophageal squamous cell carcinoma (ESCC), and non-small cell lung cancer (NSCLC)." (PMID 36875494, 2023). "A recent report proposed that SETD5 regulates glycolysis through the regulation of EP300/HIF-1a co-activators upon the hypoxic condition in breast cancer stem-like cells." (PMID 37264456, 2023). "Previous studies indicated that SETD5 expression was related to the prognosis of prostate and breast cancers, but this research is the first to indicate a correlation between SETD5 expression and NSCLC prognosis." (PMID 31345185, 2019). "Intriguingly, very little is known about SETD5 in breast cancer progression and metastasis, while TFAP2A is involved in both sporadic and hereditary breast cancer." (PMID 28086829, 2017). "SETD5 mediated the glycolysis in breast cancer stem-like cells and promoted tumor growth." (PMID 37941780, 2023). "In addition, SETD5 mediates the glycolysis in breast cancer stem cell-like cells and promotes tumor growth." (PMID 37941780, 2023). "Although the role of SETD5 in breast cancer is largely unexplored, it is possible that its upregulation by the overexpression of Usp22 may play a role in promoting aggressive cancer phenotypes." (PMID 34503086, 2021). "SET domain containing 5 (SETD5) is related to the aggressiveness of prostate and mammary cancers, but its association with non-small cell lung cancer (NSCLC) is unknown." (PMID 31345185, 2019). "SETD5 is related to the aggressiveness of prostate and mammary cancers, but the mechanism of its role in non-small cell lung cancer remains unclear." (PMID 31345185, 2019). "In addition, we found that high mRNA levels of SETD4 (p=0.0468, HR=1.92), SETD5 (p=0.00231, HR=2.79), or SETD7 (p=0.0391, HR=1.97) were significantly associated (p<0.05) with shorter survival in breast cancer patients." (PMID 25537518, 2015). "In addition, AKT1 was revealed that it could be upregulated by SET domain containing 5 in breast cancer to stimulate tumor growth and metastasis." (PMID 33511213, 2021). "Taken together, these results indicated that SETD5 may be an oncogenic factor; this finding is supported by the oncogenic role of other SET domain protein family members, except SETD2, which was demonstrated to be a tumor suppressor in renal and breast carcinomas." (PMID 31345185, 2019).
autism (7 papers, 2019 to 2024). Persistent deficits in social interaction and communication and interaction as well as a markedly restricted repertoire of activity and interest as well as repetitive patterns of behavior. "The effects of 40 Hz light flickers on other more common murine models of autism, like SETD5, mutated in 1% of the cases of autism, should be tested and compared with the current data to establish 40 Hz treatment as a clinically relevant therapy." (PMID 38740879, 2024). "This study shows that 3 genetic models of autism have similar impairments in visual threat responses, and that these are driven by potassium channel misregulation in Setd5 haploinsufficient mice." (PMID 38857283, 2024). "Previously developed genetic autism mouse models (SETD5, UBE3A, SHANK3, Timothy syndrome) also observed reduced neurite outgrowth, sometimes in concert with the reduced synaptic connectivity." (PMID 33727673, 2021). "Setd5+/− animals manifested several autism-like behaviors, including hyperactivity, cognitive deficit, and altered social interactions." (PMID 30655503, 2019). "PAF1 complex was also reported to has mutations associated with autism, suggesting a model of potential interplay among HCF-1, PAF1 and SETD5 proposed in our study may be applicable in the onset/development of certain mental diseases." (PMID 34853439, 2022). "Findings from our in vitro and in vivo experiments echo published reports of existing animal models of autism and extend those findings at the level of physiology, which in the Setd5+/− neurons and brain appear to converge on a picture of cortical hypoconnectivity." (PMID 30655503, 2019).
KBG syndrome (5 papers, 2020 to 2025). KBG syndrome is a rare condition characterized by a typical facial dysmorphism, macrodontia of the upper central incisors, skeletal (mainly costovertebral) anomalies and developmental delay. "Finally, loss of function mutation in SETD5 was identified in a patient with KBG syndrome that also presented with microcephaly." (PMID 36845425, 2023). "Intriguingly, pathogenic SETD5 variants have also been identified in patients presenting with KBG-like phenotypes (KBG designation originates from the initials of the surnames of the three families originally described with the condition)—syndromes that phenotypically overlap with KBG syndrome." (PMID 41283518, 2025). "Haploinsufficiency of another epigenetic regulator, ANKRD11, is recognized as the primary genetic cause of KBG syndrome, suggesting a functional interplay between ANKRD11 and SETD5." (PMID 41283518, 2025). "We have here surveyed studies that have analyzed mouse models related to IDD23 and KBG syndrome, namely Setd5+/− and Ankrd11Yoda mice." (PMID 36685966, 2022). "We will also address KBG syndrome, which was thought to be caused specifically by ANKRD11 (ankyrin repeat domain containing 11) gene mutations, but for which a role for SETD5 was recently suggested." (PMID 36685966, 2022). "Notably, both IDD23 and KBG syndrome patients frequently exhibit microcephaly, underscoring the crucial role of SETD5- and ANKRD11-mediated control of NSPC proliferation in maintaining proper brain development." (PMID 41283518, 2025). "More recently, a girl with KBG syndrome features but without an ANKRD11 mutation was found to harbor a non-sense mutation in SETD5." (PMID 36685966, 2022). "However, recent studies have identified SETD5 mutations in some KBG syndrome patients without ANKRD11 mutations." (PMID 36685966, 2022). "A search for novel pathogenic variants in three patients with suspected KBG syndrome who did not harbor ANKRD11 mutations resulted in the identification of an exon 1–17 deletion and frameshift mutations in SETD5." (PMID 36685966, 2022).
autism spectrum disorder (4 papers, 2019 to 2023). A spectrum of developmental disorders that includes autism, and Asperger syndrome. "In conclusion, GSFA allowed us to characterize the transcriptional effects of six autism spectrum disorder risk genes, including ADNP and SETD5, whose effects were largely missed in the original study." (PMID 37770710, 2023).
lymph node metastasis (3 papers, 2019 to 2023). "In conclusion, we found that the overexpression of SETD5 was associated with lymph node metastasis, advanced TNM stage, and poor prognosis in patients with NSCLC." (PMID 31345185, 2019). "This study showed that SETD5 was significantly correlated with lymph node metastasis, advanced TNM stage and OS in NSCLC patients." (PMID 31345185, 2019). "SETD5 was significantly correlated with advanced TNM stage (P < 0.001), lymph node metastasis (P < 0.001) and overall survival rate (P < 0.001)." (PMID 31345185, 2019). "Positive expression of SETD5 was significantly associated with advanced TNM stage (P < 0.001) and lymph node metastasis (P < 0.001) but not with age, sex, histological type, or differentiation (all P > 0.05)." (PMID 31345185, 2019).
non-small cell lung carcinoma (3 papers, 2019 to 2023). A group of at least three distinct histological types of lung cancer, including non-small cell squamous cell carcinoma, adenocarcinoma, and large cell carcinoma. "Other SETD proteins such as SETD5 have been associated with the invasion and migration of non-small cell lung cancer cells." (PMID 32042016, 2020). "SETD5 enhances the cytodryness of non-small-cell lung cancer (NSCLC) through the PI3K/Akt/mTOR pathway." (PMID 37941780, 2023). "SETD5 was detected by immunohistochemical analysis in 147 patients with non-small cell lung cancer." (PMID 31345185, 2019).
pancreatic cancer (3 papers, 2015 to 2023). "Interestingly, SETD5 has been implicated in pancreatic cancer therapy resistance." (PMID 34503086, 2021). "By contrast, the suppression of SETD5 expression leads to reduced cell growth and migration in pancreatic cancer, prostate cancer, and hepatocellular carcinoma (HCC), as well as enhanced resistance to chemotherapeutic drugs." (PMID 36875494, 2023).
prostate carcinoma (3 papers, 2015 to 2023). A carcinoma that arises from epithelial cells of the prostate gland. "SETD5 gene mutations are also associated with prostate cancer, colorectal cancer, and neuroblastoma." (PMID 36875494, 2023). "SETD5 was reported and identified as a new diagnostic marker in prostate cancer, which was consistent with our research." (PMID 30755832, 2019). "The high levels of the SETD5 gene are related to poor prognosis in patients with lung, bladder, and prostate cancer." (PMID 36875494, 2023).
adenoma (2 papers, 2013 to 2023). A neoplasm arising from the epithelium. "SETD5 expression was mainly localized in the nuclei of hyperplastic polyps, adenomas, and colon adenocarcinoma tissues, based on immunohistochemical analyses." (PMID 37963940, 2023). "Quantitative analysis of microarray data confirmed that these methyltransferases, which included Setd3, Setd5, Suv39h2, Smyd3, Prmt3, Prmt6, Nsd1, and Nsd2 were up-regulated in metastases compared to adenomas, carcinomas, or disseminated cells." (PMID 23520493, 2013).
Anxiety (2 papers, 2019 to 2022). Intense feelings of nervousness, tension, or panic often arise in response to interpersonal stresses. "This is in keeping with the observation that ASD patients carrying SETD5 mutations, as well as Setd5+/− mice, are characterized by increased levels of anxiety." (PMID 36613611, 2022). "Setd5+/− mice spent significantly reduced time in the open arms of the elevated plus maze versus wt controls (153.3 ± 15.91 vs. 99.25 ± 11.81 s, P = 0.0096), suggestive of increased anxiety." (PMID 30655503, 2019).
bladder cancer (2 papers, 2019 to 2020). "On the other hand, three genes (LAMC2, TNC, and SETD5) were found related to the survival of bladder cancer in grade 2 carcinoma." (PMID 32640634, 2020). "Through integrative analysis, we identified six HMT genes (PRDM9,ASH1L,SETD3,SETD5,WHSC1L1, and KMT2D) that may play a key role in the development and progression of bladder cancer." (PMID 30984543, 2019).
colorectal cancer (2 papers, 2023 to 2024). A primary or metastatic malignant neoplasm that affects the colon or rectum. "In this study, we found that aberrant overexpression of SETD5 in patients with colorectal cancer is associated with CD133, a cancer stem cell marker, and induces the acquisition of stem cell-like phenotypes in CRC cells." (PMID 37963940, 2023). "Our findings revealed that SETD5 is involved in various biological processes, including colorectal cancer and PI3K-AKT signaling." (PMID 37963940, 2023). "We here show that aberrant SETD5 overexpression induces stemness in colorectal cancer (CRC) cells." (PMID 37963940, 2023). "In summary, overexpression of SETD5 in colon cancer cells induces the expression of CSC marker genes, resulting in the gain of stem cell-like properties in colorectal cancer cells, such as increased survival rates and tumor-initiating ability, and the promotion of RNA Pol II O-GlcNAcylation." (PMID 37963940, 2023).
developmental delay (2 papers, 2021 to 2025). "We describe a 6-year-old girl harboring a pathogenic SETD5 gene variant, disclosed in early infancy by whole exome sequencing that was performed for global developmental delay." (PMID 40462669, 2025).
epilepsy (2 papers, 2022 to 2025). A brain disorder characterized by episodes of abnormally increased neuronal discharge resulting in transient episodes of sensory or motor neurological dysfunction, or psychic dysfunction. "Epilepsy is a frequent complication of individuals with SETD5 mutations." (PMID 36685966, 2022).
esophageal squamous cell carcinoma (2 papers, 2022 to 2023). Esophageal squamous cell carcinoma (ESCC) is a type of esophageal carcinoma (EC) that can affect any part of the esophagus, but is usually located in the upper or middle third. "SETD5 may function as a histone methyltransferase and promote cell stemness of esophageal squamous cell carcinoma and NSCLC." (PMID 35990252, 2022).
hepatocellular carcinoma (2 papers, 2023). A malignant tumor that arises from hepatocytes. "Downregulation of SETD5 restrained the tumorigenicity of the hepatocellular carcinoma (HCC) cells." (PMID 37941780, 2023).
Intellectual developmental disorder, autosomal dominant 23 (2 papers, 2022 to 2025). "Heterozygous loss-of-function mutations of the SETD5 (SET domain containing 5) gene have been identified in individuals with an NDD designated IDD23 (intellectual developmental disorder, autosomal dominant 23)." (PMID 36685966, 2022). "Intellectual developmental disorder, autosomal dominant 23 (IDDD23; MIM# 615761) is caused by heterozygous loss-of-function variants in SETD5." (PMID 40913078, 2025).
microcephaly (2 papers, 2022 to 2023). A congenital or acquired developmental disorder in which the circumference of the head is smaller than normal for the person's age and sex. "In addition to the potential role of ASH1L in the control of brain size postnatally, clinical studies suggest that mutations in either NSD1, NSD2, SETD2, or SETD5 have also been implicated in microcephaly." (PMID 36845425, 2023). "In contrast, multiple mechanisms could be implicated in microcephaly associated with deficits in SETD5." (PMID 36845425, 2023). "Similarly, defects in neuronal arborization outgrowth and complexity due to Setd5 downregulation could also be a potential mechanism contributing to SETD5-associated microcephaly." (PMID 36845425, 2023). "However, based on the current clinical literature it is not clear whether the microcephaly associated with SETD5 is congenital or postnatal." (PMID 36845425, 2023).
BAFopathy (1 paper, 2022). Disorder caused by mutations in the various subunits composing the BAF complex. "This analysis showed that TRIP12 is most closely related to the CSS9 (SOX11), BAFopathy (ARID1A, ARID1B, SMARCB1, SMARCA2, SMARCA4) and MRD23 (SETD5) episignatures." (PMID 36430143, 2022).
cardiomyopathy (1 paper, 2025). A disease of the heart muscle or myocardium proper. "The cardiomyopathy-associated targets were Dnmt1, Hdac1, Dot1l, Setd5, Nsd2, Usp3, Bap1, Prkca, Prkcb, Crebbp and Clock: 11 out of 81 (13.6% of total targets)." (PMID 40076868, 2025).